IGKV1OR2-108 (immunoglobulin kappa variable 1/OR2-108 (non-functional))
Synonyms: IGKV1/OR2-108; IGKV1OR2108; IGO1
Gene: Immunoglobulin variable (V) gene on chromosome 2 (113,406,396 to 113,406,872, forward strand). Ensembl gene ENSG00000231292.
Gene Ontology:
Biological process: immune response
Cellular component: immunoglobulin complex; extracellular region; plasma membrane
Homologues: Orthologues: mouse Igkv20-101-2 (56% identical). Paralogues in human: IGKV1-39 (90% identical), IGKV1-6 (90% identical), IGKV1D-39 (90% identical), IGKV1-17 (86% identical), IGKV1-12 (85% identical), IGKV1-27 (85% identical), IGKV1-9 (85% identical), IGKV1D-13 (85% identical), IGKV1D-12 (85% identical), IGKV1-16 (84% identical), IGKV1D-16 (84% identical), IGKV1-33 (83% identical), and 81 more.